CSAG4 (CSAG family member 4 (pseudogene))
Gene: Transcribed unprocessed pseudogene on chromosome X (152,739,864 to 152,740,681, forward strand). Ensembl gene ENSG00000242599.
Diseases named in the same sentence as CSAG4 in open-access papers:
CSAG4 is named in the same sentence as 2 diseases in open-access papers, as found by Europe PMC text mining. Sharing a sentence is not in itself a finding about the gene and the disease. The quoted sentences say what the papers report.
cancer (1 paper, 2022). A tumor composed of atypical neoplastic, often pleomorphic cells that invade other tissues. "Three pseudogenes (RPL26P29, PNLIPRP2, and CSAG4) are included in the top three miRNA–RNA pairs with the smallest p-value, and several miRNA-pseudogene pairs were found as potential prognostic pairs for all 7 types of cancer." (PMID 35430805, 2022).
CSAG4 also shares sentences with these, for which no sentence is quoted: breast carcinoma (1 paper).